TNFRSF10A-DT (TNFRSF10A divergent transcript)
Synonyms: LOC389641; PLACT1
Gene: Long non-coding RNA gene on chromosome 8 (23,224,471 to 23,230,926, forward strand). Ensembl gene ENSG00000246582.
Diseases named in the same sentence as TNFRSF10A-DT in open-access papers:
TNFRSF10A-DT is named in the same sentence as 11 diseases in open-access papers, as found by Europe PMC text mining. Sharing a sentence is not in itself a finding about the gene and the disease.
TNFRSF10A-DT shares sentences with these, for which no sentence is quoted: lung carcinoma (2 papers); pancreatic cancer (2); cancer (1); colon cancer (1); gallbladder cancer (1); lung adenocarcinoma (1); mesothelioma (1); rectal cancer (1); stomach cancer (1); thyroid cancer (1); tumor (1).